CLDND1 (claudin domain containing 1)
Description:
Plays a role in negatively regulating the permeability of cells to small molecules.
Synonyms: C3orf4; Z38; CLDN-25; GENX-3745
Tractability: Antibody: UniProt places it where antibodies can reach, with high confidence; UniProt predicts a signal peptide or a membrane-spanning region; its Gene Ontology location is reachable by antibodies, with medium confidence. PROTAC: ubiquitination databases record sites on it; its protein half-life has been measured.
Gene: Protein-coding gene on chromosome 3 (98,497,912 to 98,523,066, reverse strand). Ensembl gene ENSG00000080822.
Subcellular location: Cell junction, tight junction; Cell membrane
Subcellular location (Human Protein Atlas): Nucleoplasm; Cytosol; Nucleoli
Gene Ontology:
Molecular function: protein binding
Cellular component: cell surface; apical plasma membrane; bicellular tight junction; membrane; plasma membrane
Genetic constraint (gnomAD): Loss-of-function variants: 12 observed, 24.06 expected, observed/expected ratio (o/e) 0.5, 90% interval 0.32 to 0.81. The upper end of that interval is the gene's LOEUF score, 0.81, which puts it in group 3 of 6, group 1 being the genes least tolerant of losing a copy. Missense variants: 247 observed, 282.36 expected, observed/expected ratio (o/e) 0.87, 90% interval 0.79 to 0.97. Synonymous variants: 96 observed, 96.84 expected, observed/expected ratio (o/e) 0.99, 90% interval 0.84 to 1.17.
Homologues: Orthologues: chimpanzee CLDND1 (99% identical), macaque CLDND1 (99% identical), dog CLDND1 (95% identical), pig CLDND1 (95% identical), guinea pig CLDND1 (94% identical), mouse Cldnd1 (92% identical), rat Cldnd1 (92% identical), tropical clawed frog cldnd1 (56% identical), zebrafish cldnd1b (52% identical), zebrafish cldnd1a (51% identical).
Diseases named in the same sentence as CLDND1 in open-access papers:
CLDND1 is named in the same sentence as 20 diseases in open-access papers, as found by Europe PMC text mining. Sharing a sentence is not in itself a finding about the gene and the disease. The quoted sentences say what the papers report.
breast carcinoma (4 papers, 2015 to 2023). "Global expression analysis of basal-like breast cancer cell lines following the induction of apoptosis has suggested a link between claudin domain-containing 1 (CLDND1) and apoptosis." (PMID 35892692, 2022). "Our data provide support for a combined approach, targeting CLDND1 and other survival pathways, as a tool to elicit substantial apoptosis of breast cancer cells." (PMID 26083392, 2015). "The role of CLDND1 in breast cancer cells was validated by transfecting MDA-MB-231, MDA-MB-468, BT-549 and MCF-7 cells with three different siRNA oligonucleotides targeting CLDND1." (PMID 26083392, 2015). "In conclusion, we demonstrate a novel survival role for CLDND1 in breast cancer cell with basal-like features." (PMID 26083392, 2015). "Furthermore, CLDND1 has been reported to be overexpressed in breast cancer cells that are basal cell-like or estrogen receptor-negative." (PMID 35892692, 2022). "In this study we unravel a previously unknown role of CLDND1 in breast cancer cell apoptosis." (PMID 26083392, 2015). "Claudin domain containing 1 (CLDND1) and Caspase recruitment domain family member 6 (CARD6) were found to regulate the apoptosis in breast cancer and non-alcoholic fatty liver disease, respectively." (PMID 34344298, 2021). "Analysis of differential expression levels highlighted CLDND1, PLEKHA2, ACSL3, SLC30A9, MSN, CALM3 and PRKAR1A as potential regulators of breast cancer cell survival since they were affected by PKCδ siRNA in all cell lines." (PMID 26083392, 2015).
cerebrovascular disease (2 papers, 2019 to 2022). "The functional role of high expression levels of CLDND1 in a normal central nervous system and in cerebrovascular disease is not known, and further analysis is needed to determine the effects of gefitinib treatment on the brain tissue by suppressing CLDND1 expression." (PMID 35892692, 2022).
schizophrenia (2 papers, 2023 to 2024). A major psychotic disorder characterized by abnormalities in the perception or expression of reality. "Among the six candidate genes, four (BDH2, CLDND1, GAS8, and TRIP4) displayed DTU events in all schizophrenia samples, while the other two genes (LARP4 and NVL) showed significant DTU events in specific subgroups." (PMID 38508189, 2024). "Amongst the six candidate genes, four (BDH2, CLDND1, GAS8, TRIP4) displayed DTU events in all schizophrenia samples, while the other two genes (LARP4, NVL) showed significant DTU events in specific subgroups." (PMID 37503064, 2023).
Alzheimer disease (1 paper, 2024). A progressive, neurodegenerative disease characterized by loss of function and death of nerve cells in several areas of the brain leading to loss of cognitive function such as memory and language. "CLDND1 has been linked to Alzheimer’s disease, with one study indicating a potential correlation specifically with a subgroup of the condition." (PMID 38508189, 2024).
asthma (1 paper, 2012). "Likewise, changes in the expression levels of both CLDND1 and MUC1 are associated with the development of lung cancer; it would be interesting to assess the performance of the gene expression model in subjects with other smoking-related diseases such as lung cancer, asthma, and COPD." (PMID 23210427, 2012).
cardiomyopathy (1 paper, 2017). A disease of the heart muscle or myocardium proper. "We identified genes with alternative splicing profiles that were common to cardiomyopathy (PDLIM3, CD36, CLDND1, TTN, FAM126a, TLR4, and CD59)." (PMID 28098235, 2017).
cerebral infarction (1 paper, 2022). An ischemic condition of the brain, producing a persistent focal neurological deficit in the area of distribution of the cerebral arteries. "Meanwhile, the serum CLDND1-derived peptide antibody levels are elevated in patients with cerebral infarction when compared with healthy controls." (PMID 35892692, 2022).
Colon cancer (1 paper, 2020). "The expression of CLDND1, a tight junction protein, is shown to be highly increased in human Colon cancer samples and cell lines, and also positively correlated with tumor growth and disease progression." (PMID 33092652, 2020).
coronary heart disease (1 paper, 2023). "Four of them (CLDND1: Claudin Domain Containing 1, AHRR: Aryl Hydrocarbon Receptor Repressor, MPO: Myeloperoxidase, and PTCD2: Pentatricopeptide Repeat Domain 2), involved in lipid metabolism and inflammatory diseases, were associated with coronary heart disease." (PMID 37190071, 2023).
diabetes mellitus (1 paper, 2023). A metabolic disorder characterized by abnormally high blood sugar levels due to diminished production of insulin or insulin resistance/desensitization. "Serum antibody levels of Claudin domain containing 1 (CLDND1)-derived peptides are elevated in patients with cerebral infection, CVDs or diabetes mellitus as compared to healthy controls." (PMID 36670468, 2023).
heart failure (1 paper, 2021). Inability of the heart to pump blood at an adequate rate to meet tissue metabolic requirements. "To get the robust gene signature in heart failure, we overlapped genes from LASSO and SVM-RFE and got six gene signatures, including PALLD, DDX39A, CD164, CLDND1, SLC38A2, and CALU." (PMID 34926621, 2021).
Hypertension (1 paper, 2021). The presence of chronic increased pressure in the systemic arterial system. "CLDND1 expression predicted poor therapeutic outcomes of hypertension patients." (PMID 34248836, 2021).
lung squamous cell carcinomas (1 paper, 2012). "Interestingly, CLDND1 is also up-regulated in lung squamous cell carcinomas." (PMID 23210427, 2012).
non-small cell lung carcinoma (1 paper, 2022). A group of at least three distinct histological types of lung cancer, including non-small cell squamous cell carcinoma, adenocarcinoma, and large cell carcinoma. "The addition of gefitinib, an EGFR-TKI used in clinical practice for diseases such as non-small cell lung cancer, significantly decreased the expression of CLDND1, which was increased by EGF." (PMID 35892692, 2022).
cancer (2 papers, 2016 to 2022). A tumor composed of atypical neoplastic, often pleomorphic cells that invade other tissues. "In this study, we analyzed the regulatory mechanism of CLDND1 expression, which is involved in cancer cell proliferation and TJ formation." (PMID 35892692, 2022). "This suggests that aberrantly expressed CLDND1 can be inhibited by gefitinib treatment, in turn inhibiting the growth of these cancer cells." (PMID 35892692, 2022). "It has been demonstrated that Ras and B-Raf are known to affect MEK1/MAPK in the control of cell survival and MEK1/MAPK is tightly connected with CLDND1, Foxo3a and p21 in cancers." (PMID 26967560, 2016). "However, the effect of gefitinib on suppressing CLDND1 expression in various types of cancer cells and the kinase signaling pathway downstream of EGF signaling is yet to be elucidated, and thus is a subject for future studies." (PMID 35892692, 2022). "Thus, the targeted regulation of CLDND1 and the kinase signaling pathway may lead to the development of novel therapies for cancer." (PMID 35892692, 2022).
CLDND1 also shares sentences with these, for which no sentence is quoted: hemorrhage (1 paper); lung carcinoma (1); non-alcoholic fatty liver disease (1); Stroke (1); tumor (1).